LIF (LIF interleukin 6 family cytokine)
Diseases named in the same sentence as LIF in open-access papers (continued):
Sharing a sentence is not in itself a finding about the gene and the disease.
tumor (continued). "In addition, a significant increase in lifespan and decrease in tumor mass has been observed in KPf/fCL mice upon treatment with an anti-LIF monoclonal antibody in combination with chemotherapy." (PMID 33846527, 2021). "Similarly, in pancreatic ductal cell carcinoma, tumor cell‐secreted IL1 induces the formation of iCAF in a cascade involving increased LIF expression and activation of JAK/STAT signaling." (PMID 34218518, 2021). "Combination treatment with anti-LIF antibody (10 mg/kg twice a week) and gemcitabine (100 mg/kg once a week) was reported to result in complete tumor remissions in seven out of nine patient-xenograft mouse models (PDX), which was maintained after treatment withdrawal." (PMID 33630157, 2021). "In their study, anti-LIF antibody treatment led to tumor growth suppression and increased survival in mouse models through the reduction of pro-tumoral M2 macrophages and Tregs, as well as the increase of tumor-infiltrating CD8+ T cell and NK cells." (PMID 33630157, 2021). "In addition, it has been demonstrated that LIF was overexpressed in tumor tissue compared with healthy pancreas." (PMID 32411709, 2020). "Although LIF expression does not exhibit a significant association with tumor status, higher LIF protein levels seem to be associated with more invasive cancer behavior, such as deeper invasion and regional lymph node metastasis." (PMID 31973037, 2020). "While our results do not rule out inhibitory roles for tumor-expressed IL-6 on CD103+ cDC1 function, we anticipate CD103+ cDC1s are refractory to tumor-derived LIF or G-CSF due to the relatively low abundance of receptor mRNAs in this subset relative to other immune populations." (PMID 31947933, 2020). "LIF mediates several functions in tumor development and progression." (PMID 32651426, 2020). "Moreover, since the high number of CD8+ T cells at the tumor site is important for immunotherapy, especially using anti-PD1 Abs, LIF-neutralizing Abs in combination with anti-PD1Abs suppress tumor growth and prolong the survival of tumor-bearing hosts." (PMID 32707850, 2020). "This might be a reason for the finding that LIFR inhibition is a more efficient approach to prevent tumor formation than LIF inhibition." (PMID 32651426, 2020). "CD103+ cDC1s express relatively low amounts of Lifr and Csf3r mRNAs versus other immune subsets such as pDCs or granulocytes, respectively, suggesting they may be refractory tumor-produced LIF or G-CSF." (PMID 31947933, 2020). "Kaplan–Meier curves showed that OSCC patients with higher LIF expression, advanced stage, large tumor size, or positive lymph node metastasis had significantly shorter overall survival (p < 0.001, p = 0.011, p = 0.002, and p = 0.014, respectively; log-rank test) than others." (PMID 31973037, 2020). "Immunostaining of the tumor sections confirmed the expression of LIF and LIFR." (PMID 32651426, 2020). "LIF antibody along with gemcitabine significantly repressed tumor growth in a PDX model." (PMID 31296870, 2019). "Recent studies have demonstrated that LIF promotes tumor development and progression." (PMID 29899555, 2018). "Nevertheless, miR-500a-3p may serve as a tumor suppressor through inhibiting LIF and PAPPA, and TDP-43 might contribute to inhibiting cancer progression by modulating miR-500a-3p target genes." (PMID 28952053, 2018). "LIF is an important regulator and is frequently overexpressed in different human tumor types." (PMID 29899555, 2018). "However, we chose C26 for this study because we have already shown that LIF explains all the effect of this tumor on skeletal muscle myotube diameter in cell culture." (PMID 28993738, 2017).
tumor (continued). "In addition, serum levels of LIF in cachectic C26 tumor-bearing mice were relatively less than that used in the cell culture model, yet muscle atrophy was greater." (PMID 28993738, 2017). "The Ehrlich mouse tumor cells were the first identified source of LIF in a cancer context." (PMID 28993738, 2017). "Our previous study reported that LIF promotes the migration ability of tumor cells." (PMID 26716902, 2016). "Our recent study showed that LIF activates the AKT/mTOR signaling in tumor cells." (PMID 26716902, 2016). "It is possible that the induction of miR-21 by LIF may also contribute to the promoting effect of LIF on cell proliferation and tumor growth, which will be of interest to investigate in future study." (PMID 26716902, 2016). "In this study, we found that LIF promotes EMT in human tumor cells." (PMID 26716902, 2016). "This study reports that LIF promotes EMT in human tumor cells." (PMID 26716902, 2016). "Therefore, the de novo expression of LIF and the up-regulation of LIFR in CCA bile ducts, along with LIF overexpression in the tumor reactive stroma, indicate the presence of autocrine and paracrine LIF-mediated mechanisms in CCA." (PMID 26296968, 2015). "Considering the critical role of LIF in promoting tumor development and chemo-resistance in tumors, the specific regulation of LIF expression by HIF-2α provides foundation for future study to develop potential therapeutic strategies to block LIF overexpression in tumors." (PMID 25726527, 2015). "Immunofluorescence studies revealed, more specifically, that in the tumor reactive stroma, LIF was expressed by inflammatory cells (CD45 positive), likely including macrophages, lymphocytes and neutrophils as evaluated by immunoperoxidase, and CAF (α-smooth muscle actin (α-SMA) positive)." (PMID 26296968, 2015). "LIF production by tumor cells directly correlates with a more invasive phenotype." (PMID 26296968, 2015). "Similarly, the tumor reactive stroma surrounding the neoplastic bile ducts showed more extensive LIF immunoreactivity than the peribiliary stroma in peritumoral tissue (p < 0.001)." (PMID 26296968, 2015). "Moreover, our study shows that in addition to its role in mediating TGFβ tumor suppressor effects, LIF also acts downstream of TGFβ to prevent tumor progression by inhibiting cell migration, in a p21-independent manner." (PMID 25885043, 2015). "As expected, a significant reduction in the tumor volume was observed upon inhibition of LIF/LIFRα." (PMID 25915540, 2015). "Based on this, we hypothesize that, in our model, tumor LIF activates Jak-STAT pathway in normal epithelial cells through LIFR receptor leading to NO release and the subsequent creation of a pro-inflammatory environment." (PMID 24597571, 2014). "RAS could play a synergistic effect with LIF inducing NO production, leading to inflammation, macrophage infiltration and tumor-induced fibrosis." (PMID 24597571, 2014). "We have previously reported that tumor cell secreted LIF was able to decrease HC11 cell viability." (PMID 19615079, 2009). "We have found that 72 hours of LIF treatment induced a dose-dependent inhibition of HC11 cell survival, whereas it also caused a dose-dependent increase in the number of viable primary tumor cells." (PMID 17925034, 2007). "Interestingly, recent studies suggest that blood-borne tumor-derived leukemia inhibitory factor (LIF) and galectin-3 (Gal3) may excite the paraventricular nucleus of the hypothalamus, leading to increased sympathetic signaling." (PMID 41030446, 2025). "Additionally, we explored whether starting anti-LIF treatment earlier (on day 5 post tumor implantation, along with chemotherapy, Figure A3a) would enhance efficacy." (PMID 39857986, 2025). "Notably, LIF knockout in C26 cells greatly mitigated cachexia in tumor-bearing mice." (PMID 38245529, 2024).
tumor (continued). "In addition, recent studies suggested that LIF might be involved in metabolic regulation, which was identified as a tumor-secreted molecule that could promote adipose tissue and body weight loss in cachectic settings." (PMID 39391493, 2024). "Importantly, LIF knockout in C26 cells significantly mitigates cachexia in tumor-bearing mice." (PMID 38245529, 2024). "Thus, the tumor-derived IL-1 and LIF cooperate to promote EMH in cancer." (PMID 37141182, 2023). "However, contradictory results remain concerning the impact of LIF in tumors, highlighting the importance of considering the effect of a particular cytokine or of a cocktail of secreted factors not only on the primary tumor but also on its microenvironment." (PMID 38137514, 2023). "Examination of the impacts of LIF expression in various tumor types, while also considering its roles in normal tissue and other pathological states, is necessary to better understand the entirety of LIF signaling for the creation of effective LIF-based therapeutics." (PMID 35204717, 2022). "Based on preliminary data and published reports supporting a role for cytokine and estrogen signaling crosstalk, we sought to test the hypothesis that there is an interplay between IL6/LIF cytokine signaling in the tumor microenvironment and estrogen signaling." (PMID 36230597, 2022). "In addition to IL-6, HMC3 microglia also secreted detectable amounts of LIF and IL-11, suggesting that IL-6, LIF, and IL-11 may contribute to paracrine signaling in the MB tumor microenvironment." (PMID 35159191, 2022). "Therefore, LIF may exhibit distinctive effects not only on different cell types, but on different cellular status (e.g., tumor and normal cells)." (PMID 33888681, 2021). "In addition, LIF was shown to be superior than CA 19-9 in predicting tumor response by RECIST1.1." (PMID 33630157, 2021). "Therefore, while in vitro treatment with LIF may stimulate tumor cell proliferation, its ability to stimulate STAT3 signaling in the context of the bone microenvironment may still promote tumor dormancy, although the mechanism is unresolved." (PMID 32023849, 2020). "On the one hand, LIF activates mTORC1/p70S6K signaling via LIF receptor, leading to increased tumor growth; LIF-mediated radioresistance may result from the inhibition of DNA damage responses (DDR) signaling; EBV-encoded LMP1 can induce LIF expression through NF-κB activation in NPC cells." (PMID 32368302, 2020). "The analysis demonstrated the presence of signals in either tumor cells or the SMA-positive myofibroblasts present in the stromal component, a finding that is in line with the fact that, in addition to acting on tumoral cells, LIF also promotes the activation of cancer associated fibroblasts (CAFs)." (PMID 28415643, 2017). "In addition to its regulatory role in tumor cells, LIF promotes invasive tumor microenvironment through the activation of stromal fibroblast, which could be an important mechanism for the promoting effect of LIF on tumor invasion and metastasis." (PMID 26716902, 2016). "In this model, SDF-1 and HGF promote the recruitment and activation of stromal cells, while LIF and, possibly, SCGF-β directly target tumor cells by activating key oncogenic signaling pathways such as JAK/STAT3 and PI3K/Akt." (PMID 41597220, 2026). "In this context, the LIF/LIFR signaling axis represents a compelling and understudied pathway involved in tumor growth, immune evasion, and therapeutic resistance." (PMID 41163398, 2025). "This review aims to provide a comprehensive analysis of the current understanding of LIF and LIFR in the context of GC, highlighting molecular mechanisms of action, contributions to tumor progression, and potential as therapeutic targets." (PMID 41163398, 2025). "LIF secreted by iCAFs subsequently activates the STAT3 signaling pathway in cancer cells, which promotes tumor progression." (PMID 40136652, 2025).
tumor (continued). "In OC, ascitic fluid contains high levels of IL6 and leukemia inhibitory factor (LIF), which trigger the formation of TAM-like cells from monocytes, further promoting tumor progression and metastasis." (PMID 40427188, 2025). "In summary, our findings suggest that the combination of chemotherapy, anti-LIF, and anti-PD-L1 synergistically enhances antitumor activity in PDAC through both tumor-intrinsic and immune-mediated mechanisms." (PMID 39857986, 2025). "Bulk RNA‐seq and single‐cell RNA‐seq of 37 PC specimens revealed enrichment and positive correlation of SOX9, LIF, LIFR, and IL6ST (GP130) in tumor cells." (PMID 41163398, 2025). "Elevated expression of LIF, LIFR correlates with reduced survival in OCa patients and contributes to chemoresistance and tumor microenvironment (TME) modulation." (PMID 41154625, 2025). "Leukemia inhibitory factor (LIF) and its receptor, leukemia inhibitory factor receptor (LIFR), have been identified as being overexpressed in GC tissues; their role in tumor differentiation, lymphovascular invasion, and metastasis is under investigation." (PMID 41163398, 2025). "Research on the role of LIF in PDAC has primarily focused on aspects of tumor biology, including tumor stemness, EMT, growth, and survival." (PMID 39857986, 2025). "Inhibition of LIF was predicted to downregulate ID1-mediated functions including angiogenesis and the growth of a broad array of tumor cells." (PMID 38793603, 2024). "In summary, our data indicates that pharmacological inhibition of a positive autocrine loop of LIF/LIFR promotes ferroptosis and can inhibit OCa proliferation in vitro and tumor progression in vivo." (PMID 38789520, 2024). "Our research underscores the importance of the LIF/LIFR autocrine loop for OCa cell survival, stemness, tumor immunity, and progression." (PMID 38789520, 2024). "Circulating LIF protein was readily detected and significantly increased in HNSCC patients and markedly declined after tumor surgical resection." (PMID 39206755, 2024). "Yet, in another study, changes in circulating LIF levels, which induce an inflammatory CAF state, were closely related to tumor response to treatment." (PMID 38540204, 2024). "Navigating through the nuanced cellular machinations within the tumor microenvironment (TME), this study unearthed pivotal insights elucidating TGF-β’s capability to augment LIF expression, activated via the Smad2/3 complex." (PMID 38490994, 2024). "By leveraging information within the signatures, we discover that the HB-EGF/EGFR/MAPK axis represents a hub of tumor-stroma crosstalk, promoting the expression of CSF2 and LIF and favoring the recruitment of macrophages." (PMID 39262776, 2024). "miR-203 acts as a tumor suppressor in RMS, targeting p63 and leukemia inhibitory factor (LIF), both of which are involved in maintaining an undifferentiated state." (PMID 39594601, 2024). "M2d macrophages, also known as tumor-associated macrophages (TAMs), are induced by adenosine A2 receptor (A2AR), leukemia inhibitory factor (LIF) and IL-6, and mainly inhibit inflammatory reaction and promote angiogenesis and tumor growth." (PMID 36903624, 2023). "In our study, LIF was detected in culture supernatants of SLC cells and tumor extracts of SLC-transplanted rats, and in the rats’ sera at low levels." (PMID 37893197, 2023). "In tumor tissues and lymph nodes, the expression of T-bet, PD-1, TIM-3, and LAG-3 genes in the Anti LIF group showed a significant increase." (PMID 37393300, 2023). "The LIF receptor complex, composed of LIF, LIFR, and glycoprotein 130 (gp130), is responsible for promoting tumor growth, progression, and metastasis through the direct effect of JAK/STAT3 and other downstream pathways, such as MAPK, AKT, and mTOR." (PMID 37103052, 2023). "Leukemia inhibitory factor (LIF) exhibits significant tumor-promoting function, while its cognate receptor (LIFR) is considered to act as either a tumor promoter or suppressor." (PMID 36925915, 2023).
tumor (continued). "Studies have confirmed the oncogenic functions of LIF-LIFR in tumor stemness, progression, alterations in the tumor microenvironment and therapy resistance." (PMID 36925915, 2023). "iCAF were able to produce high levels of IL-6, IL-11, leukemia inhibitory factor (LIF), and chemokines (CXCL1, CXCL2) while myCAF, detected closer to the tumor lesions, expressed high levels of α-SMA and ACTA2 genes, CTGF and COL1A1 (TGF-β-response genes)." (PMID 37342322, 2023). "In the subset of tumor-promoting CAFs, iCAFs can participate in immune escape or directly act on pancreatic cancer cells by producing inflammatory cytokines such as IL-6, leukemia inhibitor factor (LIF), and CXCL1 to promote tumor progression." (PMID 37666813, 2023). "Increased secretion of LIF in turn activates the STAT3 signaling pathway and, therefore, WP1066 was able to suppress tumor growth and greatly improve mouse survival." (PMID 37190167, 2023). "LIF along with its receptor (LIFR) form a part of the interleukin-6 (IL-6) cytokine family LIF/LIFR signaling pathway, which plays an important role in tumor progression, stemness, and resistance to therapy." (PMID 36567312, 2022). "To explore the role of LIFR and LIF in GC, we have then assessed LIFR expression in 31 tumor samples from patients with GC and compared them to the corresponding non-neoplastic mucosa." (PMID 35847866, 2022). "We used tumor tissue arrays that contained normal (n = 33) and EEC (n = 46) tumors for IHC analyses using the LIF antibody." (PMID 36358818, 2022). "miR-637 inhibits the growth of tumor cell lines and tumor growth in xenograft animal models by targeting AKT1 in glioma and PDAC, LIF in HCC, and NUPR1 in OSCC." (PMID 36175921, 2022). "Silencing or overexpressing circFARP1 in CAFs altered the ability of CAFs to induce tumor cell stemness and GEM resistance via leukemia inhibitory factor (LIF)." (PMID 35045883, 2022). "qRT-PCR analysis revealed that the tumor derived from si-circGOLPH3-transfected UM1 cells exhibited upregulated miR-1299 expression and downregulated LIF expression, which was consistent with the results of in vitro experiments." (PMID 35481460, 2022). "We found that inhibiting interleukin-6/leukemia inhibitory factor (IL6/LIF) cytokine signaling activates estrogen signaling and blocking both pathways was synergistic in inhibiting tumor cell growth." (PMID 36230597, 2022). "In vitro, IL6/LIF increased tumor cell estrogen receptor expression and signaling, and combination cytokine blockade and AET resulted in synergistic inhibition of tumor cell growth." (PMID 36230597, 2022). "The tumor cells secreted a few C/Cs on the panel, including exclusive secretion of IL-11, and shared secretion of CX3CL1, LIF and TIMP-1 with the fibroblasts." (PMID 34572807, 2021). "A more recent study found that calcipotriol inhibited CAF proliferation and reduced secretion of pro-tumorigenic factors PGE2, leukemia inhibitory factor (LIF) and IL-6, consistent with the known anti-tumor effects of VDAs." (PMID 33868174, 2021). "LIF and LIFR are overexpressed in multiple solid tumors and LIF/LIFR signaling promotes tumor growth, metastasis, and therapy resistance." (PMID 34400617, 2021). "This engineered protein potently inhibits LIF-derived signaling and sphere formation in PDAC cells and slows tumor progression in a mouse model of disease." (PMID 33846527, 2021). "In cytokine and chemokine array analyses the overexpression of Lrp5 reduced the levels of several tumor-promoting factors in CM, including CXCL2, GM-CSF, IL6, LIF, DLK1 and MRP with an increase in IL27, a tumor-suppressing cytokine." (PMID 33859739, 2021).